IL10 (interleukin 10)
Diseases named in the same sentence as IL10 in open-access papers (continued):
Sharing a sentence is not in itself a finding about the gene and the disease.
Sepsis (continued). "We found increased levels of IL-10 in both sepsis and leptospirosis groups indicating an immunosuppressed environment and confirming previous studies in other tissues." (PMID 31114579, 2019). "Another important mechanism of sepsis-induced immune-suppression is the expansion of immunosuppressive cell populations including regulatory T lymphocytes, IL-10-producing B lymphocytes and myeloid-derived suppressor cells (MDSC)." (PMID 30730978, 2019). "As seen in whole blood samples from sepsis patients, TLR2 induction correlated with the overexpression of genes associated with immunosuppression (IL10, FPR2) or wound healing (MMP9)." (PMID 31396208, 2019). "Several cytokines also exhibited a significant sepsis × sex interaction [IL-6 (p = 0.009), IL-10 (p = 0.003), MIP-1α (p = 0.0149), KC (p = 0.003)]." (PMID 31278440, 2019). "To this end, we first performed Spearman’s correlation between the DNA methylation data and the secreted IL-10 levels, for all patients with sepsis and control individuals." (PMID 31665078, 2019). "Remarkably, similar to our observations of DN T cells and IL-10 producing B cells, the sepsis-induced increase in this immunosuppressive cell population was further enhanced in IL-7-treated septic mice." (PMID 29466409, 2018). "Network analysis revealed a network formed by PAI-1, IL-6, IL-8, MCP-1 and IL-10 on days 1, 2 and 4 throughout the acute phase of sepsis." (PMID 30228372, 2018). "Anti-inflammatory interleukins (IL-4, IL-5, IL-10) were significantly lower in sepsis patients and close to the lowest detection limit of the assays." (PMID 29379043, 2018). "High level of IL-10 in septic patients significantly correlates with sepsis and death suggesting profound immunosuppression." (PMID 29974037, 2018). "As a well-known anti-inflammatory cytokine, IL-10 was crucial in modulating excessive inflammatory response, whose high expression in early onset was beneficial to sepsis prognosis." (PMID 30104976, 2018). "Previous research utilizing IL-10 and IL-27 (an IL-12 cytokine family member) in murine models of sepsis have yielded promising outcomes directed towards the understanding of cytokine dynamics in septic shock." (PMID 29641433, 2018). "Transcripts of TH2-cytokines interleukin 4 (IL-4) and interleukin 10 (IL-10) as well as Treg-differentiation promoting transforming growth factor beta (TGF-β) were markedly increased in sepsis samples." (PMID 30332984, 2018). "All these studies show that both type-1 and type-2 diabetic animals have exacerbated hyperglycemia, and production of both pro- (TNF, IL1, IL6, MCP1) and anti-inflammatory (IL10) cytokines in experimental sepsis." (PMID 29780390, 2018). "We found that IL-6, IL-8, MCP-1 and IL-10 formed a cytokine network in the acute phase of sepsis and that the combined score of IL-6 + IL-8 + IL-10 + MCP-1 correlated with patient prognosis and disease severity." (PMID 30228372, 2018). "The application of CTCE-0214, a SDF-1α peptide analog and CXCR-4 agonist, significantly suppressed TNF and interleukin (IL)-10 concentrations and improved survival in murine systemic inflammation and sepsis." (PMID 29796010, 2018). "Monocytes and neutrophils produce IL-1β, tumor necrosis factor-α (TNF-α), and IL-10, cytokines constituting the storm during sepsis." (PMID 30538802, 2018). "In relation to the systemic profile, a significant increase was observed in the levels of TNF, IL-6, and IL-10 in animals of the sepsis group compared to the control (respectively)." (PMID 30524657, 2018). "Hendriks demonstrated that peritoneal cytokine levels (especially IL-6, TNF-α, and IL-10) were dramatically different in rats who either survived or succumbed to an intra-peritoneal sepsis model in the 24 h after cytokine determination." (PMID 29977328, 2018). "In sepsis, T cells become hypo‐responsive in terms of proliferation and turn toward a type 2 profile with an increased production of IL‐4 and IL‐10, and suppression of IL‐12 and IFN‐γ." (PMID 30238076, 2018).
Sepsis (continued). "One week and one month after sepsis induction, both the percentage and the numbers of IL-10+ cells among B cells were increased threefold in mice with sepsis compared with non-septic (sham) mice." (PMID 29466409, 2018). "Our current study focused on the effect of IL-10- and IgM-producing B-1a cells in sepsis-induced ALI." (PMID 30134811, 2018). "This study’s novel longitudinal comparison of systemic cytokines in the two separate models demonstrated that the addition of sepsis crosses predictive threshold of IL-6, IL-10, and TNF for immune dysregulation." (PMID 29849508, 2018). "Given the known impact of IL-10 and HO-1 on diminished phagocyte function, the role of HO-1 in sepsis warrants further investigation." (PMID 30046137, 2018). "In the A. baumannii sepsis model, we observed high IL-10 levels under hypoxia after 4 h of infection." (PMID 30082478, 2018). "Many earlier studies found that IL-10 promotes survival in sepsis and endotoxin shock, consistent with our results indicating beneficial effects of IL-10 in LPS-induced shock." (PMID 29621339, 2018). "Recent studies have shown that blocking IL-10, or IL-10 deficiency, promotes resistance to GBS sepsis in part by restoring neutrophil recruitment to sites of infection." (PMID 29520354, 2018). "Growing evidence indicates that genetic polymorphisms in genes encoding inflammation-related cytokines, including IL-6, IL-10 and TNF-α, play significant roles in the pathogenesis of sepsis and even contribute to sepsis susceptibility and progression." (PMID 30268141, 2018). "The early onset of pro-inflammatory cytokine storm, often contributing to the lung injury in sepsis, can be reversed by the actions of anti-inflammatory cytokines such as interleukin (IL)-10." (PMID 30134811, 2018). "This mixed early peak in both pro-(IL-6 and TNF) and anti-inflammatory (IL-10) cytokines between time of insult (trauma, hemorrhage, and/or sepsis) and day 1 has been seen in inflammatory stimuli animal models as well as clinical sepsis studies." (PMID 29849508, 2018). "Equilibrium between TNF-α, IL-1β and anti-inflammatory IL-10 has been proven highly dynamic and dependent on genetic heterogenity in human sepsis and SIRS." (PMID 29304171, 2018). "IL-10 can work as a counter regulatory cytokine as in the setting of lipopolysaccharide (LPS)-induced sepsis whereby LPS-induced IL-10 can inhibit expression of proinflammatory cytokines and also inhibit signaling of pattern recognition receptors." (PMID 30176916, 2018). "Murine B-1a cells are known to produce ample amount of IL-10 and granulocyte macrophage colony stimulating factor (GM-CSF), which attenuate excessive inflammation during sepsis." (PMID 30134811, 2018). "The spectra of PBMCs from septic patients matched with those of interferon-γ- and interleukin-10-stimulated PBMCs, confirming that sepsis is characterized by both inflammatory and immunoregulatory features." (PMID 30064357, 2018). "During sepsis, the levels of IFNγ, IL-6, IL-10, and IL-4 were significantly elevated in the moderate preterm group only." (PMID 30555806, 2018). "Beside these in vitro findings, we demonstrated the beneficial role of B-1a cells during sepsis through the production of anti-inflammatory cytokine IL-10." (PMID 30134811, 2018). "At day 8 after inoculation, surviving mice developed splenomegaly with a significant increase in the spleen mass and increased levels of IL-10 in serum, characteristic of the immunosuppressive phase of sepsis, were observed." (PMID 30123776, 2018). "To examine if increased numbers of IL-10 producing B cells are a long-term outcome of sepsis, we performed IL-10 staining in CD19+ B cells from the spleens of septic and control mice." (PMID 29466409, 2018). "In contrast to what we observed in the sepsis model, at the time of the death of the mice, we observed lower IL-10 levels under hypoxia (P < 0.05)." (PMID 30082478, 2018).
Sepsis (continued). "A similar pattern of decreased TNFα, IL-6, IFNγ, and IL-10 was also observed in a post-mortem study of stimulated splenocytes from patients who died of sepsis." (PMID 30555806, 2018). "Our findings suggest that MCP-1, sCD14, IL-6, IL-10, cortisol, and HBP are modulated by the source of sepsis and that elevated MCP-1 and cortisol plasma levels are associated with sepsis-induced organ dysfunction." (PMID 29769838, 2018). "IL-10 has furthermore been demonstrated to play a critical step in the progression to a lethal state of sepsis and that endogenous production of IL-10 delays the onset of mortality in CLP induced sepsis." (PMID 29204105, 2017). "Another important observation supporting our paradigm was decreases inimmunosuppressive IL-10 cytokine and increased microbial clearance from peritoneum inS100A9 knockout mice during late sepsis." (PMID 29204146, 2017). "In line with this, increased systemic IL-10 levels correlate with the sepsis score and death in patients." (PMID 28241480, 2017). "The frequency and the absolute number of splenic CD4+Foxp3+ Treg cells were marked reduced in Il10−/− sepsis-surviving mice at day 15 after CLP." (PMID 28374774, 2017). "Here the authors show expansion of the Treg cell population in sepsis mice is driven by IL-33-induced ILC2 activation of IL-10 production by macrophages." (PMID 28374774, 2017). "The shared variance of IL-8, IL-6, and IL-10 (factor 2 in factor analysis) was correlated with the development of sepsis." (PMID 28769538, 2017). "There was no statistical significance on the levels of IL-1β, IL-6, IL-2sR and IL-10 in sepsis-non AKI group compared with the control." (PMID 28296904, 2017). "Sepsis was associated with increased TNF-α and IL-10 levels in the hypothalamus and higher IL-1β, IL-6, and IL-10 in the brainstem." (PMID 27229490, 2017). "In our study, baseline immune parameters including decreased monocyte HLA-DR expression, higher plasma G-CSF level, higher plasma IL-10 level, and lower serum SeMo ratio were independent predictors of 28-day mortality in sepsis patients." (PMID 29073262, 2017). "At onset of infection, SIRS-N patients had the lowest median IL10/TNF ratio (1.2) with progressively increasing value as severity of sepsis increased, at 1.5, 3.0, and 4.5 for patients with sepsis, severe sepsis, and septic shock, respectively." (PMID 31058274, 2017). "Continued overexpression of IL-10 contributes to the immunosuppressive environment that characterizes later stages of sepsis." (PMID 28628637, 2017). "In contrast, wild-type and S100A9 knockout miceproduced small amounts of the immunosuppressive IL-10 during early sepsis, butsignificantly increased during late sepsis in the wild-type mice and not in knockoutmice." (PMID 29204146, 2017). "At 5-10 months after sepsis diagnosis, sepsis survivors have significantly more circulating Foxp3+ Treg cells and also higher concentrations of IL-33 and IL-10 in their serum compared to those of the healthy controls." (PMID 28374774, 2017). "IL10 is responsible for potentiating the compensatory anti-inflammatory environment that has been termed the “immune-paralysis” phase of sepsis which can occur early and simultaneously during the pro-inflammatory cytokine storm." (PMID 31058274, 2017). "In our study, filgrastim administration apparently upregulates the systemic release of IL-8, IL-6, and IL-10 on the first day of fever, with little impact on sepsis discrimination capability." (PMID 28769538, 2017). "Previous researches reported that higher plasma IL-10 concentration contributed to higher mortality of sepsis." (PMID 28628675, 2017). "TNF-α is the primary inflammatory mediator in sepsis as it regulates other downstream cytokines such as IL-6 and IL-10." (PMID 28086962, 2017). "We have previously shown that 4 days after induction of sepsis, splenic DCs still maintain their bias toward increased IL-10 synthesis." (PMID 29218051, 2017).
Sepsis (continued). "It has been shown that administrations of recombinant IL-10 confer significant therapeutical protection in experimental models of sepsis." (PMID 28978926, 2017). "Interleukin-10 plays a major role in the resolution of inflammation during sepsis and infection but is also involved in persistence of pathogens by interfering with innate and adaptive immunity." (PMID 28883891, 2017). "Nemeth at al. reported that MSCs attenuate sepsis in a mouse model via the PGE2 pathway by reprogramming host macrophages to increase their IL-10 production." (PMID 28446249, 2017). "Interleukin-1β (IL-1β), IL-6, IL-10 and tumor necrosis factor-α (TNF-α) are some of the classical sepsis-associated cytokines." (PMID 28176831, 2017). "IL-10 attenuates the proinflammatory response in sepsis and decreases mortality in some animal model." (PMID 28298812, 2017). "Concordantly, sepsis-surviving Rag1−/− mice, which had increased the polarization of M2 macrophages, also showed elevated concentration of IL-10 in the lungs." (PMID 28374774, 2017). "In neutrophils, sepsis-related effects include immature neutrophil release, increased IL-10 secretion, and others." (PMID 29073262, 2017). "Altogether, these data indicate that IL-10 derived from M2 macrophages is required for Treg cells expansion and, consequently, for the immune dysfunction in sepsis-surviving mice." (PMID 28374774, 2017). "Bone marrow stromal cells have been shown to modulate the activation of host macrophages through prostaglandin E2 to promote the secretion of more IL-10 and protect against sepsis in mice." (PMID 29117205, 2017). "IL-33, released during tissue injury in sepsis, activates type 2 innate lymphoid cells, which promote polarization of M2 macrophages, thereby enhancing expansion of the Treg cell population via IL-10." (PMID 28374774, 2017). "IL-10 overexpression on sepsis day 1 is suggestive of the overt anti-inflammation that is predictive of poor outcome." (PMID 29073262, 2017). "We have previously shown that BMC from septic mice when cultured in the presence of GM-CSF in vitro give rise to BMDC that resemble splenic DCs during sepsis in terms of increased IL-10 synthesis." (PMID 29218051, 2017). "Collectively, these data indicate that IL-33/ST2 and IL-4/IL-13/STAT6 signalling are required for the expansion of Treg cells in sepsis-surviving mice, linking IL-10-secreting M2 macrophage in this process." (PMID 28374774, 2017). "Interleukin-10 (IL-10) secretion and lymphocyte exhaustion are the main features of sepsis-induced immunosuppression." (PMID 28628675, 2017). "In agreement with data from M2 polarization kinetics, we found an increased concentration of IL-10 in the lungs of sepsis-surviving mice by day 3 after CLP, remaining elevated over the course of observation." (PMID 28374774, 2017). "It has been reported that the PD-1/PD-L1 system is involved in lymphocyte apoptosis and IL-10 production in sepsis." (PMID 28705256, 2017). "Some studies have correlated the protective effects of IL-10 on sepsis with factors such as: septic process induction methodology (LPS-lipopolysaccharide or LPC-ligation and cecal puncture) and time of intervention." (PMID 29257842, 2017). "Sepsis-surviving patients had significantly higher concentrations of IL-33 and IL-10 in their serum and more circulating Treg cells compared to those of the healthy controls." (PMID 28374774, 2017). "The concentration of inflammatory cytokines (TNF-a, IL-6, MCP-1 and IL-10) were dramatically increased in plasma and peritoneum in mice under sepsis." (PMID 28273909, 2017). "Inflammatory cytokines like TNF-α and HMGB1 were increased, while anti-inflammatory cytokines like IL-10 were decreased in sepsis." (PMID 27413421, 2016). "More studies are needed to determine the role of low-dose steroid therapy on IL-10 production in patients with severe sepsis." (PMID 27555669, 2016).
Sepsis (continued). "The anti-inflammatory cytokines IL-4 and IL-10 were elevated in 8/11 PT infants with sepsis and in 7/12 VPT infants with sepsis (P > 0.05, χ2 test), resulting in 15/23 identified infants with sepsis." (PMID 27293317, 2016). "Inflammatory cytokines (TNF-α, IL-6, and HMGB1) were increased, while anti-inflammatory cytokines (IL-10) were decreased in sepsis." (PMID 27413421, 2016). "Severe sepsis/septic shock were associated with the IL6 rs1800795 GC-CC and IL10 rs1800896 G/G genotypes." (PMID 27725770, 2016). "Regarding TNFα, IL-6, IL-10, sTNFr, our results confirm that both pro-inflammatory and anti- inflammatory responses occur early and simultaneously in human sepsis as well as after mild CLP procedure in mice." (PMID 27574993, 2016). "Plasma levels of TNF-α, IL-6, and IL-10 were strongly increased after 3 and 6 hours from LPS administration, as well as after sepsis induction in the CLP model, in comparison to those measured in saline-injected or sham-operated mice." (PMID 26963510, 2016). "IL-10 and sTNFr secretion at the onset of sepsis, T-cells decreased count and proliferation and Treg cells up-regulation are consistent with what has been observed in humans." (PMID 27574993, 2016). "Significantly, higher plasma endotoxin and IL-10 levels were observed in cases carrying variant TLR4+896A/G allele and severe sepsis." (PMID 27861595, 2016). "High plasma endotoxin/IL-10-related HLA-DR down-regulation and impaired phagocytosis of CD16- (classical, phagocytic) monocytes also resulted in increased severe sepsis risk among TLR4+896A/G and CD14-159C/T variant allele carriers." (PMID 27861595, 2016). "Inflammatory cytokines (TNF-α, HMGB1, IL-1β, IL-6, and IL-8) were increased while anti-inflammatory cytokines (IL-10) were decreased, in serum and lung in sepsis patients." (PMID 27413421, 2016). "The IL-10 values for the PT group were 0.457 ± 0.60 pg/mL, 107.5 ± 147.40 pg/mL, and 2.25 ± 5.54 pg/mL at presepsis, sepsis, and postsepsis, respectively (P = 0.002, Friedman test)." (PMID 27293317, 2016). "It has been reported that Tim-3 blockage in vivo increased IL-10 expression in a mouse sepsis model." (PMID 27554340, 2016). "The levels of C-RP, SC5b-9 (innate immune response mediators), and IL-10 or IL-4 (anti-inflammatory cytokines) were elevated during sepsis in both groups." (PMID 27293317, 2016). "Few differences according to HIV status were observed, but one of these studies reported higher plasma IL-10 in the presence of unaltered IL-6 among HIV-positive patients with sepsis." (PMID 27719675, 2016). "Commonly expressed genes were significantly associated with several canonical pathways known to be involved in sepsis pathogenesis, including over expression of IL-1 signaling, IL-10 signaling and TREM-1 signaling." (PMID 26871709, 2016). "In clinical practice, the IL-10: TNF-α ratio is one recommended biomarker used to monitor the progression of sepsis." (PMID 27556404, 2016). "IL-10 is the main anti-inflammatory cytokine in sepsis and thought to self-limit inflammatory processes." (PMID 25844479, 2015). "In contrast, in sepsis patients during the first 4 days of the ICU stay there was a time-dependent decline in plasma IL-6, IL-8 and IL-10 (P <0.0001 for all analytes), which are well-known cytokine markers in sepsis." (PMID 26603530, 2015). "A significant decrease (P = 0.005) of IL-10 serum concentration was found between sepsis (32.82 ± 36.91 pg/ml) and viremia (12.60 ± 26.47 pg/ml)." (PMID 26315105, 2015). "Several authors have shown that IL10 plays a crucial role in ET control, whereas others have reported a weak effect of IL10 in sepsis-induced tolerance." (PMID 26441484, 2015). "Antigen presenting cells particularly macrophages and dendritic cells produce IL-10; this is important during inflammatory response to sepsis and infection." (PMID 25834308, 2015).